SST (somatostatin)
Diseases named in the same sentence as SST in open-access papers (continued):
Sharing a sentence is not in itself a finding about the gene and the disease.
Anorexia (2 papers, 2021 to 2024). Lack of desire to eat (loss of appetite). "Data derived in a mice model suggest that hypothalamic somatostatin may be associated with a Val-deficient diet as a central mechanism of anorexia." (PMID 33925439, 2021).
anxiety disorder (2 papers, 2022 to 2024). A category of psychiatric disorders which are characterized by anxious feelings or fear often accompanied by physical symptoms associated with anxiety. "Kindling as a metaphor for development of anxiety disorders suggests somatostatin plays important regulatory roles in anxiety disorder-related phenomena of hyperexcitability in the amygdala to threat and a dampening of hippocampal and medial prefrontal cortex function." (PMID 35993088, 2022).
asthma (2 papers, 2021 to 2023). "In summary, the use of native somatostatin in the treatment of asthma is limited because of its wide range of action through all receptors, but selective agonists acting on the SST4 receptor offer some promise." (PMID 34948451, 2021). "The expression of SST significantly correlated with Asthma, Tyrosine metabolism, Systemic, lupus erythematosus, Amphetamine addiction, Regulation of lipolysis in adipocytes, Ubiquitin mediated proteolysis, Nucleocytoplasmic transport, Cell cycle, Base excision repair, Fanconi anemia pathway." (PMID 38239411, 2023). "Some of the studies described in the review based on animal models so far have shown beneficial effects in reducing asthma symptoms by activating nociception NOP1, bombesin BRS-3 and somatostatin SST4 receptors, or blocking the NPY-Y1 receptor." (PMID 34948451, 2021).
Barrett esophagus (2 papers, 2012 to 2020). Esophageal lesion lined with columnar metaplastic epithelium which is flat or villiform. "Based on the fact that the columnar epithelium of the stomach harbours substantial amounts of somatostatin cells (D cells), it came as no surprise that we found SSTRs in adenocarcinomas and Barrett's oesophagus, but not in SCC." (PMID 22550583, 2012).
brain tumors (2 papers, 2020 to 2023). "This signaling mechanism of SST could be a plausible way of exerting an antiproliferative effect in brain tumours." (PMID 38203605, 2023). "SST and its SSTR subtypes are expressed at higher levels in various malignancies, including brain tumours." (PMID 38203605, 2023).
co-infection (2 papers, 2014 to 2019). "In addition, co-infection of Ngn3- and Mafa-induced formation of both glucagon+ (Gcg) and somatostatin+ cells, which are distinct from each other." (PMID 24714494, 2014).
colon adenocarcinoma (2 papers, 2010 to 2024). "This was confirmed by studies on an animal model (male rats with 1,2-dimethylhydrazine dihydrochloride-induced colonic adenocarcinoma), which showed only a few SST-positive cells." (PMID 38540191, 2024). "The latest bioinformatic analysis indicates six hub genes, including SST and SST2, that were significantly downregulated in colon adenocarcinoma compared to controls." (PMID 38540191, 2024).
cortical dysplasia (2 papers, 2022 to 2023). "For the first time, we revealed the role of hippocampal somatostatin-positive interneurons in cortical dysplasia-related seizures." (PMID 37193687, 2023). "A reduction in parvalbumin and somatostatin cells has been reported in human GG tissues, and this phenomenon was suggested to trigger hyperexcitability in an animal model of cortical dysplasia." (PMID 36538906, 2022).
frontotemporal dementia (2 papers, 2021). Frontotemporal dementia (FTD) comprises a group of neurodegenerative disorders, characterized by progressive changes in behavior, executive dysfunction and language impairment, as a result of degeneration of the medial prefrontal and frontoinsular cortices. "Future studies need to assess PV cell activity in hA30P mice but also other interneuron populations such as somatostatin-expressing cells, which were found to be hyperactive in a murine model of frontotemporal dementia." (PMID 33347975, 2021). "Paradoxically, in an amyotrophic lateral sclerosis (ALS) and frontotemporal dementia (FTD) mouse model, hyperactive somatostatin interneurons led to disinhibition of layer 5 pyramidal neurons and excitotoxicity." (PMID 33649380, 2021).
gastric tumour (2 papers, 2018 to 2023). "A high methylation level of the SST promoter region and silencing of SST transcript has been observed in gastric tumour samples, potentially associated with gastric carcinogenesis." (PMID 38203605, 2023).
Glucose intolerance (2 papers, 2018 to 2025). Glucose intolerance (GI) can be defined as dysglycemia that comprises both prediabetes and diabetes. "While NMN treatment ameliorated glucose intolerance in obese HFD-fed mice, Sirt2 knockdown partially negated the blood glucose-lowering effects of NMN in a glucose tolerance test when endogenous insulin secretion was inhibited by somatostatin administration." (PMID 29296001, 2018).
inflammatory bowel disease (2 papers, 2021 to 2024). A spectrum of small and large bowel inflammatory diseases of unknown etiology. "SST, as an inflammatory inhibitory peptide, has potential importance in the pathogenesis of inflammatory bowel diseases (IBDs)." (PMID 34829972, 2021).
injury (2 papers, 2018 to 2025). Damage inflicted on the body as the direct or indirect result of an external force, with or without disruption of structural continuity. "Our findings suggest that, in addition to PV+ neurons, SST+ interneurons in the BLA play complex roles in modulating neuropathic pain following nerve injury and may serve as a potential target for future neuromodulation interventions in chronic pain management." (PMID 40881825, 2025).
Kaposi's sarcoma (2 papers, 2022 to 2023). A malignant neoplasm characterized by a vascular proliferation which usually contains blunt endothelial cells. "The role of SST as an anti-angiogenesis peptide emerged from past studies describing the prevention of Kaposi’s sarcoma (KS) tumour xenografts’ growth in nude mice and inhibition of angiogenesis in a PTP-dependent manner." (PMID 38203605, 2023). "High concentrations of SST (1 μM) antagonised Kaposi’s sarcoma cells conditioned medium-induced ERK phosphorylation in EA.hy926 and BAEC." (PMID 35328517, 2022).
kidney damage (2 papers, 2023 to 2024). "Because of the risk of radiotoxicological kidney damage, special precautions must be taken in clinical practice in patients treated with radiolabeled peptides such as somatostatin analogs, which include an infusion of selected amino acids or other protective measures." (PMID 37242479, 2023). "Research suggests that the growth hormone-insulin-like growth factor–SST system may play a crucial role in nephropathies, including DN." (PMID 39583850, 2024).
lung carcinoid (2 papers, 2024). "In another study, it was proved that the widespread expression of key somatostatin and ghrelin system components in lung carcinoids was associated with the clinical–histological features." (PMID 39337308, 2024). "C cells of the normal thyroid gland and the disseminated endocrine cells of a typical lung carcinoid were also SST-positive." (PMID 39518025, 2024).
Lupus (2 papers, 2004 to 2023). "This study was designed to compare basal serum growth hormone, insulin-like growth factor-1 and somatostatin levels in female systemic lupus erythematosus patients to a group of normal female subjects." (PMID 15496230, 2004). "Although lesser ODs were detected for ANA, TG2, TG6, heparin, α-myosin, chondroitin sulfate, Lupus RO-60, fibrinogen, tyrosinase, β catenin, thyroid peroxidase, claudin 7, sulfatides, somatotropin, S100B, somatostatin and actin, their p values were still very, very significant." (PMID 37845267, 2023). "Previous studies suggested that defects in the hypothalamic/pituitary axis contributed to systemic lupus erythematosus disease progression which could also involve growth hormone, insulin-like growth factor-1 and somatostatin function." (PMID 15496230, 2004).
lymph node metastases (2 papers, 2024 to 2025). "Moreover, tumour tissue investigation may need, other than Ki‐67, hormonal immunohistochemical characterisation since different functional types (such as gastrin‐producing or somatostatin‐producing or ordinary non‐functioning types) may have different risks of lymph node metastases." (PMID 40524475, 2025).
lymphoma (2 papers, 2003 to 2025). A malignant (clonal) proliferation of B- lymphocytes or T- lymphocytes which involves the lymph nodes, bone marrow and/or extranodal sites. "Dietary modification (medium-chain triglycerides, total parenteral nutrition) and somatostatin analogs have been used in selected cases to reduce chyle flow, though data are limited in lymphoma-related effusions." (PMID 41194848, 2025).
metabolic syndrome (2 papers, 2018 to 2020). A cluster of metabolic risk factors for CARDIOVASCULAR DISEASES and TYPE 2 DIABETES MELLITUS. "Our study suggests that the polymorphism in the SST gene promoter is associated with the onset of metabolic syndrome." (PMID 30053852, 2018). "Our study shows that the length of the SST poly-T repeat polymorphism is significantly associated with the expression of metabolic syndrome components, as well as the metabolic syndrome diagnosis itself." (PMID 30053852, 2018). "The aim of this study was therefore to investigate the relationship between the poly-T repeat polymorphism in the promoter of the SST gene and the expression of metabolic syndrome components." (PMID 30053852, 2018). "Previous linkage analyses and association studies led us to target the somatostatin (SST) gene as a potential candidate with a significant position in the metabolic syndrome-associated gene network." (PMID 30053852, 2018). "In a follow-up study, the authors found that the poly-T repeat polymorphism is also associated with the expression of metabolic syndrome components, indicating that this genetic alteration may induce somatostatin gene expression." (PMID 32545257, 2020). "More analyses are needed to document the mechanisms that could underlie genetic regulation effect of SST on metabolic syndrome components and to clarify its specific role." (PMID 30053852, 2018). "The aim of this study was therefore to evaluate the association between polymorphic T sequences in the promoter of the SST gene and metabolic syndrome expression." (PMID 30053852, 2018). "Analyses showed that means, frequencies and odds ratio of metabolic syndrome components expression increase as the number of poly-T repeats in the promoter region of SST increases." (PMID 30053852, 2018). "The SST gene is located on chromosome 3q27, a quantitative trait loci (QTL) associated with multiple representative traits of metabolic syndrome." (PMID 30053852, 2018). "In addition, low levels of SST have been reported to have effects on the progression of metabolic syndrome components." (PMID 30053852, 2018). "The hypothesis that an increase in the number of T repeats could act by increasing SST output is appealing, but more research is needed to better understand the processes that determine the genetic regulation of SST on metabolic syndrome components and particularly, to clarify its specific role." (PMID 30053852, 2018).
multiple endocrine neoplasia type 1 (2 papers, 2013 to 2025). An autosomal dominant tumor predisposition syndrome caused by pathogenic variants in the MEN1 gene, characterized by an increased risk of tumors of the parathyroid glands, pituitary gland, and foregut neuroendocrine tumors (most commonly pancreatic islet cells). "These have focussed mainly on the production of gastrin that can be associated with Zollinger-Ellison syndrome and multiple endocrine neoplasia type 1 (MEN1) syndrome or of somatostatin that may be associated with a unique psammomatous tumor in patients with neurofibromatosis." (PMID 40553402, 2025). "They derive from the somatostatin-producing delta cells of the pancreas or the endocrine cells of the digestive tract and may be sporadic (93.1%) or familial (6.9%) in association with NF1, multiple endocrine neoplasia type 1 (MEN 1), and Von Hippel-Lindau syndrome." (PMID 24286013, 2013).
non-small cell lung carcinoma (2 papers, 1994 to 2017). A group of at least three distinct histological types of lung cancer, including non-small cell squamous cell carcinoma, adenocarcinoma, and large cell carcinoma. "We investigated the effects of our synthetic bombesin/gastrin-releasing peptide (GRP) antagonists and somatostatin analogue RC-160 on the growth of human small-cell lung carcinoma (SCLC) and non-small-cell lung carcinoma (non-SCLC) lines in nude mice." (PMID 7947094, 1994).
osteoporosis (2 papers, 2022 to 2024). A condition of reduced bone mass, with decreased cortical thickness and a decrease in the number and size of the trabeculae of cancellous bone (but normal chemical composition), resulting in increased fracture incidence. "In these patients, the observed deficiency can lead to an increased risk of osteoporosis and osteopenia; this risk is further exacerbated by analogous molecules of somatostatin administered to some of these patients, causing a reduced adsorption of vitamin D taken with the diet." (PMID 38732007, 2024).
osteosarcoma (2 papers, 2008 to 2012). A usually aggressive malignant bone-forming mesenchymal neoplasm, predominantly affecting adolescents and young adults. "Previous studies maintain that treatment with growth hormone and somatostatin affects the growth of osteosarcoma in animal models." (PMID 18783595, 2008). "Further research is necessary to demonstrate the importance of this finding and its clinical relevance, since there is also evidence from animal studies that treatment with growth hormone and somatostatin affects the growth of osteosarcoma in animal models." (PMID 18783595, 2008).
pancreatic adenocarcinoma (2 papers, 2018). "Somatostatin (SST), a small cyclic neurpeptide, has been applied for treating pancreatic adenocarcinoma in pre-clinical trials as adjuvants on account of their inhibitory effects on cell proliferation and growth hormone release." (PMID 29596435, 2018).
parathyroid tumors (2 papers, 2019). "Cytoplasmic SST1 and SST5 were the most abundantly expressed SST subtypes in parathyroid tumors." (PMID 31336364, 2019). "All SST subtypes were to some degree expressed in parathyroid tumors." (PMID 31336364, 2019).
periodontitis (2 papers, 2019 to 2023). An acute or chronic inflammatory process that affects the tissues that surround and support the teeth. "Somatostatin has been found to play a role in periodontitis, or inflammation of the gums; it is believed that somatostatin may be involved in the inflammatory process that leads to periodontitis." (PMID 36982508, 2023). "Since SST has been shown to be antiproliferative, antiangiogenetic, and proapoptotic, our study suggests that SSTR2 might play a critical role in the aetiopathogenesis of periodontitis." (PMID 30609928, 2019).
prediabetes (2 papers, 2019 to 2020). "Our results thus provide insight into the activity of the delta cell in health and prediabetes and a possible mechanism for somatostatin to effectively exert its potent suppressive effects on islet beta and alpha cells and thereby act as an efficient modulator of glucose homeostasis." (PMID 31420552, 2019).
proliferative diabetic retinopathy (2 papers, 2008 to 2020). Advanced retinopathy due to diabetes mellitus characterized by the formation of new vessels in the retina. "Cortistatin (CST), a neuropeptide with strong structural and functional similarities to somatostatin, is abundant in the vitreous fluid, and it is decreased in patients with proliferative diabetic retinopathy." (PMID 18709137, 2008).
prostate tumor (2 papers, 2022 to 2023). "The expression of SSTRs has been shown on prostate tumour cells extensively; therefore, SST or its analogue critically regulates the growth of prostate tumours." (PMID 38203605, 2023).
psoriasis (2 papers, 2016 to 2018). An autoimmune condition characterized by red, well-delineated plaques with silvery scales that are usually on the extensor surfaces and scalp. "A dysfunctional expression and/or distribution of a great number of neuropeptides (e.g., substance P, somatostatin, vasoactive intestinal peptide) has been demonstrated in psoriasis." (PMID 27455241, 2016). "The potential clinical relevance of our present experimental data is that H2S content of the sulfurous mineral waters can induce significant elevation of plasma somatostatin level and presumably that it is responsible for anti-inflammatory effects that can be observed in patients with psoriasis." (PMID 30224931, 2018).
retinal diseases (2 papers, 2011 to 2014). "By limiting the amount of glutamate available to glutamate receptors, SST and its analogs may exert neuroprotection against glutamate neurotoxicity, which characterizes many retinal diseases." (PMID 25268135, 2014). "By limiting the amount of glutamate available to glutamate receptors, somatostatin and its analogues may exert a neuroprotective function against glutamate neurotoxicity, which characterizes many retinal diseases." (PMID 21896184, 2011).
retinal ischemia (2 papers, 2018 to 2021). A ischemic disease that involves the retina. "It is known that endogenous SST released from capsaicin-sensitive nerves prevented retinal ischemia/reperfusion injury in a mouse model." (PMID 34803662, 2021).
sarcoidosis (2 papers, 2017 to 2019). Sarcoidosis is a multisystemic disorder of unknown cause characterized by the formation of immune granulomas in involved organs. "This short communication provides a rapid overview of initial findings concerning the application of 68Ga-labeled somatostatin based receptor hybrid imaging in the diagnosis of (cardiac) sarcoidosis activity." (PMID 29782604, 2017).
schistosomiasis (2 papers, 2005 to 2014). An infectious disease caused by parasitic trematodes of the genus Schistosoma that colonize human blood vessels and release eggs that can cause granulomatous reactions leading to acute (swimmer's itch or acute schistosomiasis syndrome) or chronic disease. "Based on these reports we presented the hypothesis that exogenous administration of somatostatin could alleviate the pathology caused by schistosomiasis." (PMID 15949036, 2005). "Our experiments reveal an antifibrotic effect of somatostatin in schistosomiasis." (PMID 15949036, 2005).
small cell lung carcinoma (2 papers, 2018 to 2020). Small cell lung cancer (SCLC) is a highly aggressive malignant neoplasm, accounting for 10-15% of lung cancer cases, characterized byrapid growth, and early metastasis. "BB, NTS, and VIP stimulate the growth of small cell lung cancer (SCLC) cells whereas SST inhibits growth." (PMID 30008698, 2018).
status epilepticus (2 papers, 2018 to 2022). Status epilepticus is defined as a continuous seizure lasting more than 30 min, or two or more seizures without full recovery of consciousness between any of them. "Furthermore, in status epilepticus, depletion or ‘neurochemical exhaustion’ of reserves of neuropeptides, galanin and SST, and an increase in neurokinin and endocytosis of receptors, is recognized." (PMID 29608654, 2018). "Early anticonvulsant treatment with MK-801 or thiopental after the initial KA-induced status epilepticus prevented the subsequent increases in NPY and somatostatin levels." (PMID 36311021, 2022).